CCL2 (C-C motif chemokine ligand 2)
Diseases named in the same sentence as CCL2 in open-access papers (continued):
Sharing a sentence is not in itself a finding about the gene and the disease.
neuroblastoma (continued). "CCL2 contributes significantly to the pathogenesis of a number of cancers, including neuroblastoma, and other inflammatory conditions." (PMID 37964011, 2023). "The in vivo efficacy of anti-CCL2 antibody and etoposide against neuroblastoma was assessed following resection of primary tumors formed by two cell lines or a patient-derived xenograft (PDX) in immunodeficient NOD-scid gamma mice." (PMID 37964011, 2023). "In conclusion, inhibition of CCL2 suppresses CCL2-dependent cell migration of neuroblastoma cells and monocytes." (PMID 37964011, 2023). "MYCN amplification results in the downregulation of CCL2 in neuroblastoma cells, which seems involved in NK and T cells infiltration." (PMID 36923280, 2022). "The result in designing CAR-T cells to co-express CCR2b (the major isoform of the CCL2 chemokine receptor) showed that T cells homed to CCL2-expressing neuroblastoma and malignant pleural mesothelioma xenografts, respectively." (PMID 36466874, 2022). "CCL2 and HLA class I genes were found more often downregulated in neuroblastoma tumors with MYCN amplification." (PMID 36923280, 2022). "Blocking experiments demonstrate that CCL2 is responsible for these CCR2-expressing cells recruitment by MYCN-nonamplified neuroblastoma, as already observed for the migration of CCR2-expressing NKT cells toward CCL2-expressing neuroblastoma." (PMID 36923280, 2022). "Downregulation of HuD not only increased the level of CCL2 in neuroblastoma cells and the brain of HuD knockout (KO) mice, but also increased the susceptibility of cells to stress-induced cellular senescence." (PMID 35411051, 2022). "First, we observed a high level of CCL2 expression in neuroblastoma compared with that in the healthy adrenal gland and embryonic neural cristae cells (p < 0.05) by analyzing the GSE96631 dataset." (PMID 34778046, 2021). "The investigators found that CARS coexpressed with the chemokine receptor CCR2b had improved homing and anti-tumor activity to CCL2-secreting neuroblastoma, compared to CCR2-negative CARs." (PMID 30736355, 2019). "This suggests a model by which neuroblastoma cells that interact with monocytes produce increasing levels of CCL2, which in turn may attract more monocytes and neuroblastoma cells to sites of metastasis." (PMID 37964011, 2023). "Further investigation into in vivo extracellular CCL2 concentration gradients may add further clarity to the TME of neuroblastoma and its role in the progression of metastatic disease." (PMID 37964011, 2023). "In this study, we demonstrate that anti-CCL2 antibody suppresses in vitro monocyte and neuroblastoma migration to CCL2, and when combined with chemotherapy, improves survival in our tumor resection mouse model of neuroblastoma." (PMID 37964011, 2023). "Finally, the neuroblastoma tumor resection mouse model of minimal residual disease was utilized to study the efficacy of anti-CCL2 antibody on survival." (PMID 37964011, 2023). "Although the variability of TAMs present in the untreated control group limited significance, the trend observed in this data suggests that anti-CCL2 antibody may have the potential to decrease TAMs at sites of neuroblastoma." (PMID 37964011, 2023). "Altogether, our results suggest that CCL2 produced by neuroblastoma cells initiate the recruitment of monocytes, myeloid and plasmacytoid DCs, and that among these cells, the CD1c+ subset when activated may recruit T cells by means of CCL19/CCL22 secretion." (PMID 36923280, 2022). "An increase of CCL2 by HuD knockdown was also observed in human neuroblastoma SH-SY5Y cells." (PMID 35411051, 2022). "Neuroblastoma with low CCL2 expression may be unable to induce DC and iNKT recruitment, leading to immune escape by ignorance." (PMID 36923280, 2022). "Further preclinical work will be needed to define drugs that could restore CCL2 expression by neuroblastoma tumors, to favor immune cells recruitment, and immunologic response of high-risk neuroblastoma." (PMID 36923280, 2022).
neuroblastoma (continued). "In addition, it was observed that type I NKT cell infiltration in neuroblastomas was associated with CCL2 expression on tumor cells, indicating that expression of homing receptors on tumors was essential for infiltration of type I NKT cells in neuroblastoma." (PMID 29535734, 2018). "Also, in xenograft tumor models of mesothelioma and neuroblastoma, the genetic introduction of CCR2 in T cells resulted in increased T cell infiltration in tumors secreting CCL2 and was associated with significantly increased anti-tumor activity." (PMID 27096098, 2016). "CCL2 has recently been shown to mediate iNKT cell migration into human neuroblastoma." (PMID 20593019, 2010). "Additionally, no studies have previously examined the role of CCL2 and carlumab in high-risk neuroblastoma." (PMID 37964011, 2023). "Moreover, previous studies have shown that neuroblastoma can secrete high levels of CCL2." (PMID 36466874, 2022). "Our results suggest that CCL2 is crucial for the initial recruitment of monocytes, MDC and PDC by neuroblastoma, and paves the way for the further recruitment of effector cells in these tumors." (PMID 36923280, 2022). "A lower correlation was observed between CCL2 level and monocytes/macrophages, and PDC (IRF7) infiltration, suggesting the involvement of CCL2/CCR2 in APC recruitment by neuroblastoma tumors." (PMID 36923280, 2022). "Here, we demonstrated that HuD knockdown upregulated CCL2 expression in both mouse neuroblastoma N2a cells and human neuroblastoma SH-SY5Y cells, suggesting a potential role of HuD as a negative regulator of CCL2 expression." (PMID 35411051, 2022). "The local accumulation of C-C motif chemokines, such as CCL2, CCL7, and CXCL1, as well as the hypoxic milieu of neuroblastoma, results in the recruitment of high numbers of myeloid cells." (PMID 33917501, 2021). "CCL2 was also found to promote apoptosis and secretion of TNF-α and IL-1β in neuroblastoma SH-SY5Y cells and inhibit cell viability, while the knockdown of CCL2 exerted the opposite effects." (PMID 30761072, 2019). "In our study, we identified four chemokines, CCL2, CCL4, CCL21, and CXCR3, in neuroblastoma samples, which may originate from different cellular subsets." (PMID 40718780, 2025). "In vitro, anti-CCL2 antibody did not affect cell proliferation but significantly inhibited neuroblastoma cell and monocyte migration towards an increasing CCL2 concentration gradient." (PMID 37964011, 2023). "CHLA-255 neuroblastoma cells exhibited significant movement towards an increasing concentration gradient of CCL2, compared to tumor cells with no CCL2 and CCL2 with no concentration gradient." (PMID 37964011, 2023). "Supernatants derived from 1:1 co-culture of any of four neuroblastoma cell lines (SH-SY5Y, CHLA-255, NGP, SMS-KCNR) with MACS-purified monocytes contained significantly higher levels of CCL2 protein than supernatant isolated from culture of either monocytes or neuroblastoma cells alone." (PMID 37964011, 2023). "Altogether, these results demonstrate the major involvement of the CCR2/CCL2 axis in the recruitment of APC by MYCN-nonamplified neuroblastoma." (PMID 36923280, 2022). "Studies have found that both subtypes of MDSCs along with monocytes and neutrophils are recruited by chemokines, including C-C Motif Chemokine Ligand 2 (CCL2), CCL7, and chemokine (C-X-C motif) ligand 1 (CXCL1), produced by tumor cells and TAMs in neuroblastoma and other tumors." (PMID 32983125, 2020). "CCR2 (expressed by NKT cells) and CCL2 (expressed by a subset of MYCN non-amplified neuroblastoma cells) mediated homing of NKT cells to neuroblastoma was shown in subset of neuroblastoma patients." (PMID 31620124, 2019). "Our study demonstrates that tertiary lymphoid structure (TLS)-related genes play a crucial role in neuroblastoma (NB) prognosis, with a 6-gene TLS signature (CCL2, CCL4, CCL21, CD200, CXCR3, and IGSF6) serving as a promising prognostic biomarker for NB." (PMID 40718780, 2025).
neuroblastoma (continued). "Moreover, addition of antagonistic anti-CCL2 antibody to these assays did not affect the results demonstrating that the anti-CCL2 antibody does not have a cytotoxic effect on neuroblastoma tumor cells." (PMID 37964011, 2023). "However, the efficacy of anti-CCL2 antibody in preventing metastatic disease in neuroblastoma has not been studied." (PMID 37964011, 2023). "Moreover, neuroblastoma cells cultured in monocyte supernatant produced more CCL2 protein than neuroblastoma cells cultured without monocyte supernatant, although concentration levels were approximately a log lower than from monocytes." (PMID 37964011, 2023). "Neuroblastoma cells were found to have the greatest migration towards an increasing extracellular concentration gradient of CCL2, compared to experimental conditions which had no CCL2 or CCL2 without a concentration gradient." (PMID 37964011, 2023). "Furthermore, TAMs in non-amplified tumors activate STAT3 in neuroblastoma cells, upregulating c-Myc that reciprocally induces CCL2 secretion, forming a positive feedback loop." (PMID 38087370, 2023). "In MYCN-nonamplified neuroblastoma, CCL2 produced by neuroblastoma cells induces the recruitment of antigen-presenting cells (DCs and monocytes/macrophages), allowing infiltration by T cells, in link with CCL19 and CCL22 production, hence favoring immune responses." (PMID 36923280, 2022). "We also observed a continuum of CCL2 expression with low CCL2 expression in some MYCN-nonamplified neuroblastoma, suggesting that other mechanisms could repress CCL2 transcription." (PMID 36923280, 2022). "The NB-tag mouse model, resembling human non-amplified neuroblastoma, recruits TAMs, myeloid cells, and plasmacytoid DCs through CCL2 signaling." (PMID 38087370, 2023). "It has been shown that CCL2 expression is repressed in MYCN-amplified neuroblastoma cells, and our analysis using two different public transcriptomic datasets confirm that CCL2 transcription was lower in MYCN-amplified neuroblastoma (which may arise from tumor or immune cells)." (PMID 36923280, 2022). "The CCL2/CCR2 axis is pivotal for recruiting monocytes, myeloid cells, and plasmacytoid DCs in MYCN-nonamplified neuroblastoma." (PMID 38087370, 2023). "Overall, our findings highlighted a major role for CCL2/CCR2 axis in monocytes, myeloid and plasmacytoid cells recruitment toward MYCN-nonamplified neuroblastoma, and suggest that the recruited myeloid DCs will further recruit T lymphocytes by means of CCL19 and CCL22." (PMID 36923280, 2022). "Overall, our findings highlight a major role for CCL2/CCR2 axis in monocytes, myeloid and plasmacytoid cells recruitment toward MYCN-nonamplified neuroblastoma, allowing further immune cell recruitment, and show that these tumors present a microenvironment that can favor DC responses." (PMID 36923280, 2022). "We observed that the migration of monocytes, myeloid and plasmacytoid DC induced by MYCN-nonamplified neuroblastoma supernatants was abrogated by the addition of anti-CCL2 antibodies, demonstrating the involvement of the CCR2/CCL2 axis in their recruitment by these tumors." (PMID 36923280, 2022). "Albeit not investigated in neuroblastoma, studies in solid tumors show that the axis can be disrupted either by inhibiting CCR2 or via anti-CCL2 antibodies, thereby preventing the recruitment of suppressive myeloid cells and initiation of their tumor-promoting effects." (PMID 33917501, 2021).
liver cancer (39 papers, 2019 to 2026). An epithelial or non-epithelial malignant neoplasm that arises from the liver. "A variety of cancers (lung, breast, liver cancer) highly expressed CCL2, and usually it was associated with poor prognosis." (PMID 36747118, 2023). "Blocking CCL2/CCR2 signaling pathway can block the recruitment of monocytes and M2 polarization of tumour-associated macrophages (TAMs) in liver cancer." (PMID 39816386, 2024). "CCL2 is secreted by hepatocytes or hepatic stellate cells and is involved in liver injury, hepatitis, and liver cancer." (PMID 37904170, 2023). "The association between the expression of genes in the CCL2/CCR2 and CXCL8/CXCR2 axes and patient OS in the TCGA liver cancer dataset was analyzed." (PMID 36403057, 2022). "Among these chemokines, CCL2 has been established to play a key role in the occurrence and development of liver cancer by aggregating monocytes and macrophages into tumor tissue as well as stimulating tumor cell survival and immune escape." (PMID 36203448, 2022). "CCL2 (C–C motif chemokine ligand 2) is overexpressed in liver cancer; it can drive the recruitment of macrophages." (PMID 34335756, 2021). "Thus, the CCL2/CCR2 axis and the Hh signaling pathway play an important role in the progression of HCC, and CCL2 can also stimulate proangiogenic effects that further promote liver cancer progression." (PMID 40145607, 2025). "The article suggests that CCL2-dependent macrophage infiltration and M2-like polarization, along with the upregulation of PD-L1 in tumor cells, represent the potential mechanisms by which SLFN11 deficiency facilitates immune evasion in liver cancer." (PMID 39558948, 2024). "CCL2 can promote the malignant growth and metastasis of human liver cancer." (PMID 37895145, 2023). "Similarly, a U-shape relationship of NE/EPI concentration to CCL2 expression was also found in liver cancer cells, BMDMs, and G-MDSCs, suggesting that moderate NE/EPI level and activation of SNS/β-AR signaling led to better CCL2 control." (PMID 34593796, 2021). "The murine model of liver cancer indicated that FAP+ cancer-associated fibroblasts (CAFs) are the main source of chemokine (C-C motif) ligand 2 (CCL2), and fibroblast STAT3-CCL2 signaling inhibited tumor growth through enhanced recruitment of myeloid-derived suppressor cells." (PMID 34490078, 2021). "Lentiviral knockdown of CCL2 or the CCR2 inhibitor CCX872 significantly attenuated ETV4-induced invasion of TAMs and MDSCs and metastasis of liver cancer." (PMID 39816386, 2024). "It is remarkable that depleting all macrophages by injecting clodronate liposomes promoted liver cancer development, opposite to the tumor-suppressing effect of blocking TAM recruitment by anti-CCL2 antibody." (PMID 36828281, 2023). "To further confirm these results, we compared the expression levels of the CCL2/CCR2 and CXCL8/CXCR2 genes in HCC tumors and adjacent normal tissues using data from the TCGA liver cancer database." (PMID 36403057, 2022). "The results showed that CCL2, CCR2, CXCL8, and CXCR2 were more highly expressed in adjacent normal tissues than in liver cancer tissues." (PMID 36403057, 2022). "Using the 20 HCC tissues that were collected from HBV- and HCV-negative male HCC patients by the Taiwan Liver Cancer Network, the mRNA expression of TLR4, IL6 and CCL2 was determined using the quantitative polymerase chain reaction (qPCR)." (PMID 35955552, 2022). "It has been shown that tumor-derived CCL2 supports tumor growth, depending on CCR2 expression by host cells in mouse models of transferred liver cancer cells." (PMID 34804061, 2021). "In liver cancer, OIS hepatocytes secrete CCL-2 that attracts CCL-2+ myeloid cells to the tumor site." (PMID 34746270, 2021). "Third, the combined inhibition of CCL2 and IL13 profoundly impeded metastasis in our in vivo experimental model of liver cancer." (PMID 31933479, 2020).
liver cancer (continued). "In addition to its impact on monocyte and macrophage trafficking, CCL2 can also attract NK cells expressing its receptor CCR249, as has been previously shown in senescent liver cancer lesions." (PMID 37142692, 2023).
nephritis (39 papers, 2006 to 2025). Inflammation of renal tissue. "Around 90% of renal Ccl2 was localized within cortical tubules and most of them get damaged during induced nephritis." (PMID 33540898, 2021). "Urinary CCL2 can be used as a biomarker of kidney inflammation." (PMID 34369383, 2021). "In addition, urinary CCL2 can be used as a biomarker for kidney inflammation and these specific levels may be related to the extent of proteinuria." (PMID 37908345, 2023). "Consistently, our in vivo data showed that the expression levels of CCL2, CCL3, CCL4, CCL5, CCL19, and CXCL10 increased in the kidney of MRL.Faslpr mice during the development of nephritis." (PMID 37567910, 2023). "B1R blockade has also been reported to reduce renal inflammation by downregulating renal CCL2, CCL5, and CCL7 in the anti-GBM nephritis model." (PMID 30621761, 2019). "Consistent with our study, systemic overexpression of NOV increased the expression of MCP-1/CCL2 and regulated on activation normal T cell expressed and secreted (RANTES), within glomeruli in rats with progressive anti-Thy1.1 nephritis." (PMID 26367310, 2015). "We hypothesized that inhibiting QC/isoQC activity would lead to the degradation of CCL2, thereby ameliorating CKD and reducing kidney inflammation." (PMID 33159802, 2021). "In addition to fibrotic markers, the glomerular mRNA expression of Ccl2 is increased in the control mice with anti-GBM glomerulonephritis, and this increase is reduced in Rosa-CTGF cKO mice with nephritis." (PMID 30123390, 2018). "Expression of Fn1, Acta2, Tgfb1, Adgre1 or Ccl2 was tended to be reduced in Rosa-CTGF cKO mice with nephritis, but not significant." (PMID 28191821, 2017). "In addition to the increases in the expression levels of fibrotic makers such as Tgfβ1, Acta2, and Fn1, the glomerular mRNA expression of MCP-1 (Ccl2) and F4/80 (Adgre1) is increased in the control mice with anti-GBM nephritis, and this increase is reduced in the Rosa-CTGF cKO mice with nephritis." (PMID 30123390, 2018). "The glomerular Ccl2 and Adgre1 expression and the M1/M2 macrophage marker ratio were decreased in Rosa-CTGF cKO and Pdgfra-CTGF cKO mice, indicating that CTGF expression particularly in mesangial cells is critical to induction of inflammation in anti-GBM nephritis." (PMID 28191821, 2017).